LRRK2 (leucine rich repeat kinase 2)
Diseases named in the same sentence as LRRK2 in open-access papers (continued):
Sharing a sentence is not in itself a finding about the gene and the disease.
progressive supranuclear palsy (20 papers, 2008 to 2026). A rare late-onset neurodegenerative disease characterized by supranuclear gaze palsy, postural instability, progressive rigidity, and mild dementia. "LRRK2 is a validated targetfor devastating diseases such as Parkinson’sdisease and progressive supranuclear palsy, characterized by increasedactivity, expression, or mutations of LRRK2." (PMID 40112026, 2025). "LRRK2 is linked with tau pathology by the association of genetic variation at the LRRK2 locus with survival in the primary tauopathy progressive supranuclear palsy (PSP)." (PMID 40661559, 2025). "Common variation at the LRRK2 locus has also been linked with disease progression in a primary tauopathy, progressive supranuclear palsy (PSP)." (PMID 33915162, 2021). "On rare occasions, LRRK2 mutations may be present in progressive supranuclear palsy or atypical parkinsonian patients; however, we did not identify any pathogenic mutations in these patients." (PMID 31324919, 2019). "However, LRRK2 mutations may be associated with diverse pathologies in patients with Parkinson’s syndrome including tau pathology resembling progressive supranuclear palsy (PSP)." (PMID 35815712, 2022). "Recently, we discovered that common genetic variation near the LRRK2 locus determined survival in progressive supranuclear palsy (PSP)." (PMID 41987507, 2026). "More recently, LRRK2 was highlighted as a genetic contributor to disease progression in the primary tauopathy progressive supranuclear palsy." (PMID 38020716, 2023). "More recently, LRRK2 was highlighted as a genetic contributor to disease progression in the primary tauopathy progressive supranuclear palsy (PSP)." (PMID 35815712, 2022). "One rare case with LRRK2 p.R1441H has been related to progressive supranuclear palsy." (PMID 30333048, 2018). "Notably, polymorphisms within the LRRK2 locus are associated with PD susceptibility and the age at onset (AOO) in progressive supranuclear palsy, and these may influence LRRK2 expression, protein interactions, and kinase activation." (PMID 39062657, 2024).
autoimmune disease (17 papers, 2014 to 2025). A disorder resulting from loss of function or tissue destruction of an organ or multiple organs, arising from humoral or cellular immune responses of the individual to their own tissue constituents. "More recently, SNPs in LRRK2 were associated with cancer and inflammatory conditions (including infectious and autoimmune diseases)." (PMID 34135785, 2021). "Furthermore, recently it was shown that dopamine inhibits TRAF6-mediated NF-κB activation and inflammation via the D5 dopamine receptor in macrophages, and mutations in the LRRK2 gene are also found in some bacterial infections and autoimmune disorders." (PMID 34511867, 2021). "Supporting our claim, a genome-wide association study reported that LRRK2 mutations, as the most common genetic cause of both familial and sporadic PD, has a role in regulating inflammatory responses systemically and in the brain, and are associated with autoimmune diseases." (PMID 34511867, 2021). "Increased prevalence of autoimmune diseases relative to other PD groups was found in a Norwegian sample of 100 LRRK2 carriers, and included three individuals (3%) diagnosed with MS." (PMID 39175765, 2024). "Apart from PD, LRRK2 has been a hot topic of discussion for autoimmune diseases such as IBD, type 1 diabetes, rheumatoid arthritis, celiac disease, psoriasis, and multiple sclerosis, which LRRK2 modulates multiple pathways in innate and adaptive immunity by hindering NF-κB and NF-AT signaling." (PMID 40629324, 2025). "Furthermore, the involvement of LRRK2 in some autoimmune diseases strongly suggests a prominent role of LRRK2 in inflammation and probably neuroinflammation." (PMID 40076730, 2025). "In addition, the LRRK2R1627P mutation or knockout causes autoimmune diseases and malignant tumors, suggesting that LRRK2R1627P and LRRK2-/- rats have higher mortality due to tumors." (PMID 39500355, 2024). "LRRK2 was also found not protective in the autoimmune disease systemic lupus erythematosus, since LRRK2 levels in B cells positively correlated with disease severity." (PMID 32410948, 2020). "A resent genome-wide association study has identified several shared loci (including HLA-DRB5, LRRK2, and MAPT) between PD and 7 autoimmune diseases (including psoriasis, rheumatoid arthritis, and so on), suggesting that there were some common genetic risks between PD and autoimmune diseases." (PMID 31929812, 2019).
melanoma (17 papers, 2010 to 2025). A malignant, usually aggressive tumor composed of atypical, neoplastic melanocytes. "A previous study has reported an increased melanoma risk among patients with PD having LRRK2 mutations." (PMID 40860809, 2025). "In contrast, a meta-analysis by Lee and colleagues (2022) concluded that LRRK2-associated PD was linked to a lower likelihood of lung and colorectal cancers but a greater risk of brain cancer and melanoma." (PMID 41300754, 2025). "Melanoma incidence in PD patients carrying LRRK2 gene mutations who had a heterozygous p.Gly2019Ser pathogenic variant was similar or even higher than the risk of the development of melanoma among patients with idiopathic PD." (PMID 37629650, 2023). "A meta-analysis by Lee and co-authors (2022) showed that PD patients carrying LRRK2 gene mutations displayed a decreased risk of lung and colorectal cancer cancers and a higher risk of brain cancer and melanoma." (PMID 37629650, 2023). "In B16-F10 mouse melanoma cells, Rab38 drives LRRK2 membrane association and overexpressed kinase-active LRRK2 shows striking pericentriolar recruitment, which is dependent on the presence of endogenous Rab38 but not Rab32 or Rab29." (PMID 37625589, 2023). "The connection between LRRK2 mutations and melanoma development remains inconclusive." (PMID 40860809, 2025). "Recently, LRRK2 has been associated with an increased risk in some cancers, in particular melanoma." (PMID 22361010, 2012). "Further exploration of this relationship is warranted to better comprehend the interplay between LRRK2, α-syn pathology, and melanoma development." (PMID 40860809, 2025). "Rab38 but not Rab32 or Rab29 drives pericentriolar recruitment of exogenous kinase-active LRRK2 in B16 melanoma cells." (PMID 37625589, 2023). "Such literature data are very scarce for LRRK2, while the only existing literature on the association between GBA and melanoma was focused on Gaucher disease patients." (PMID 37629650, 2023). "Rab38 knockdown decreased LRRK2 membrane association in melanocytes and disrupted pericentriolar recruitment of overexpressed LRRK2 in B16-F10 melanoma cells." (PMID 37625589, 2023). "Loss of heterozygosity of PARK2, LRRK2 mutations causing neuronal cell death and neurotoxicity, BRAF kinase alterations, and PARK7 oncogene activation with subsequent melanoma development are possible underpinning genetic pathophysiologiy." (PMID 35247252, 2022). "In order to better understand the epigenetic regulation of Lrrk2, Inpp4b, and Adcy3 in our murine melanoma model, we analyzed the ERBBS and expression data for CpG resolution methylation levels." (PMID 35075772, 2022). "To examine the effects of TRIM1 on endogenous LRRK2 levels, we used human melanoma Malme-3M cells, which express relatively high levels of both LRRK2 and TRIM1 mRNA (NCBI GEO profiles IDs #86805339 and #86784306)." (PMID 35266954, 2022). "A global phosphoproteomic study of a melanoma tumouridentified phosphorylation of LRRK2 at Ser935 as one of 5600 phosphorylation sitescatalogued on 2250 proteins, but this was not investigated further." (PMID 20659021, 2010). "Furthermore, some PD-related genes, such as Parkin, alpha-synuclein, LRRK2 and DJ-1, were also found to play critical roles in the pathogenesis of melanoma." (PMID 26535116, 2015). "The prevalence of LRRK2 G2019S (the most common genetic determinant of PD) is not increased in patients with melanoma, but a recent study showed an almost 3-fold increased risk of non-skin cancers in LRRK2 G2019S mutation carriers." (PMID 21203498, 2010). "Interestingly, demographical data suggest an increased incidence of cancer in individuals with a germline G2019S LRRK2 mutation, in particular, melanoma; however, findings are not consistent across all studies." (PMID 32722212, 2020).
melanoma (continued). "However, a recent study could not verify a correlation between the LRRK2 mutation and the development of malignant melanomas in either symptomatic PD patients or asymptomatic carriers, and no SNCA gene was identified in patients with a malignant melanoma history." (PMID 40243562, 2025). "In contrast, B16-F10 mouse melanoma cells (“B16 cells”) produce melanosomes, indicating that pathways of LRO biogenesis are active and express high levels of endogenous Rab32, Rab38, and LRRK2." (PMID 37625589, 2023). "We analyzed LRRK2, ADCY3, and INPP4B DNA methylation and expression profiles in human melanoma cohorts to determine whether the murine model data are applicable to human melanoma biology." (PMID 35075772, 2022). "LRRK2 is known to interact with proteins in the cellular environment, including proteins involved in MAPK signaling pathway, a pathway frequently disrupted in melanoma." (PMID 35075772, 2022).
breast carcinoma (15 papers, 2018 to 2025). "Interesting results were obtained by dividing the patients by gender, showing increased cancer risk in female PD patients and female LRRK2 carriers, along with increased breast cancer risk in female PD patients compared to healthy controls." (PMID 41300754, 2025). "Literature data indicate that carriers of the G2019S mutation in LRRK2 have an increased cancer risk (including blood, brain and breast cancer)." (PMID 37629650, 2023). "A specific LRRK2 rs10878441 CC genotype has been linked to a poorer prognosis in Chinese breast cancer patients." (PMID 35247252, 2022). "• The LRRK2 rs10878441 CC genotype is associated with poor prognosis of breast cancer in a Chinese population." (PMID 33658398, 2021). "It has been found that the LRRK2 G2019S mutation was associated with an increased risk of skin and breast cancer and the R1441C/G mutation, with the risk of colon cancer and hematological cancers." (PMID 33066407, 2020). "A significant association between the LRRK2 mutation and breast cancer in women adjusted was also seen (OR 4.58; 95% CI 1.45–14.51; p = .010)." (PMID 29568677, 2018). "It has also been attempt to unravel if the association between breast cancer and the LRRK2 mutation was limited to PD patients." (PMID 29568677, 2018). "After removing the breast cancer cases, a non‐significant association between harboring a LRRK2 mutation and cancer when adjusting for age and sex was found (OR 1.73; 95% CI 0.90–3.36; p = .103)." (PMID 29568677, 2018). "Our findings suggest that the C allele of LRRK2 has poor prognosis in breast cancer." (PMID 33658398, 2021). "LRRK2 expression may be regulated in a variety of ways, while the association between the SNP rs10878441 and the prognosis of breast cancer might be caused by differential microRNA regulation." (PMID 33658398, 2021). "LRRK2 mutation carriers have an increased risk of non‐skin cancer compared with iPD subjects, which was mainly driven by the association between harboring the mutation and breast cancer in women." (PMID 29568677, 2018). "Lack of information on hormonal and reproductive factors may confound the association between LRRK2 mutations and breast cancer." (PMID 29568677, 2018). "In conclusion, the LRRK2 rs10878441 CC genotype is associated with poor prognosis of breast cancer in a Chinese population, suggesting that it could be a potential prognostic biomarker for breast cancer." (PMID 33658398, 2021). "The C allele cannot be targeted by miR-550-3p, leading to an increase expression of LRRK2 protein, thereby altering the prognosis of breast cancer." (PMID 33658398, 2021). "MM was not among the cancer types that have been firmly linked to LRRK2 mutations like breast cancer in women, colon and skin malignancies or leukemia." (PMID 37629650, 2023). "Comparing patients with IPD and patients with LRRK2-PD, the latter had a significantly increased risk of breast cancer, hormone-related cancers, and non-skin cancer." (PMID 33066407, 2020). "The group suggested that LRRK2 G2019S does not predispose to breast cancer in the absence of PD in a Western European population." (PMID 29568677, 2018). "Our study included only ethnic Norwegians, indicating the increased breast cancer risk is independent of ethnicity in the presence of the LRRK2 mutation." (PMID 29568677, 2018). "The Leucine-rich repeat kinase 2 (LRRK2) rs10878441 CC genotype is associated with poor prognosis of breast cancer in a Chinese population and may be used as a potential prognostic biomarker for breast cancer." (PMID 33658398, 2021). "It has been shown that LINK-A interacts with PKT6 and LRRK2 and thereby promotes HIF-1α phosphorylation and protein stabilization under normoxic conditions in breast cancer cells." (PMID 34877935, 2021).
breast carcinoma (continued). "LINK-A promotes HIF1α phosphorylation at tyrosine 565 and tryptophan 797 loci by regulating BRK and LRRK2; this process leads to the activation of HIF1α signals under normoxia conditions in triple-negative breast cancer (TNBC), resulting in glycolysis restructuring and breast cancer tumorigenesis." (PMID 32878637, 2020).
Dyskinesia (15 papers, 2008 to 2025). A movement disorder which consists of effects including diminished voluntary movements and the presence of involuntary movements. "Severe wearing-off and dyskinesia with off-time pain have been reported in a LRRK2 pathogenic variant carrier." (PMID 38020640, 2023). "Among the PD patients with LRRK2 mutations, they were more likely to be referred for surgery because of severe dyskinesia." (PMID 35754954, 2022). "Among responsive patients, almost 35% of LRRK2 mutation carriers developed dyskinesias and motor fluctuations, more severe and frequent in p.R1441C/G/H/S mutation." (PMID 36291241, 2022). "An association between the occurrence of dyskinesias and LRRK2 (leucine-rich repeat kinase 2) G2019S gene mutations has recently been suggested." (PMID 26831335, 2016). "LRRK2-PD patients are also at risk for developing motor fluctuations, dyskinesias and dystonia." (PMID 39199492, 2024). "We then adjusted for sex, age, and disease duration in a logistic regression model, which confirmed the association between LRRK2 mutations and dyskinesia and motor fluctuations (dyskinesia: OR = 2.9, 95% CI = 1.14–7.12, P = 0.022; motor fluctuations: OR = 3.4, 95% CI = 1.29–9.75, P = 0.016)." (PMID 39420034, 2024). "Similarly, several variants in the LRRK2 gene have been associated with the risk of motor fluctuations and levodopa-induced dyskinesias." (PMID 36291241, 2022). "When the presence of dyskinesia and dystonia was controlled for the presence of PARKIN homozygous/compound heterozygous or LRRK2 mutations, the result for dyskinesia remained significant [dyskinesia: p = 0.007, OR 4.37 (95%CI 1.49–12.85)], but it became non-significant for dystonia (p = 0.088)." (PMID 32714263, 2020). "Moreover, a higher levodopa-equivalent dose (LED) and a higher proportion of levodopa-induced complications, including motor fluctuations and dyskinesia, were also observed in PD patients with the LRRK2 G2385R variant in some studies." (PMID 30123490, 2018). "Although the incidence of dyskinesia was similar in both groups, the time to onset was longer in patients with mutations in LRRK2 than in patients with idiopathic PD (8·4 years [SD 4·6 years] vs 5·6 years [SD 3·7 years], difference 2·8 years, 95% CI 2·3–3·3 years; p<0·0001)." (PMID 18539534, 2008). "Genetic factors are more commonly observed in LD‐induced dyskinesias, such as LRRK2, PARK2 (parkin), PARK6 (pink‐1), and PARK7 (DJ‐1)." (PMID 40785408, 2025). "In a recent study, the profile of PD patients with LRRK2 mutations that undergo DBS was recorded; among this group of patients, younger age of onset, longer disease duration and dyskinesia were commonly present." (PMID 39199492, 2024). "LRRK2 p.G2019S-associated PD is a more benign progression than idiopathic PD as patients with idiopathic PD need dopamine-replacement treatment earlier than patients with LRRK2 p.G2019S were more prone to drug-induced dyskinesia." (PMID 25391693, 2014). "We found that LRRK2 mutations were associated with an increased risk of dyskinesia and motor fluctuations compared to mutation-negative PD." (PMID 39420034, 2024). "There was also Levodopa-induced dyskinesia in one patient who carries both the LRRK2 p.G2019S and parkin exon 5 duplication: this was marked peak-dose dyskinesia of choreic type involving extremities (with gait being almost impossible) and accompanied by dystonic anterocollis." (PMID 25391693, 2014). "Furthermore, patients with idiopathic PD needed dopamine-replacement treatment earlier than patients with LRRK2 Gly2019Ser did and were more prone to drug-induced dyskinesia." (PMID 18539534, 2008). "The motor symptoms (eg, disease severity, rate of progression, occurrence of falls, and dyskinesia) and non-motor symptoms (eg, cognition and olfaction) of LRRK2-associated PD were more benign than those of idiopathic PD." (PMID 18539534, 2008).
Dyskinesia (continued). "Nonetheless, while LRRK2 G2019S carriers have more levodopa-induced dyskinesia (p = 0.002), the statistical significance lacked on multivariate analysis (OR = 1.965, p = 0.217)." (PMID 28465860, 2017).
frontotemporal dementia (14 papers, 2010 to 2025). Frontotemporal dementia (FTD) comprises a group of neurodegenerative disorders, characterized by progressive changes in behavior, executive dysfunction and language impairment, as a result of degeneration of the medial prefrontal and frontoinsular cortices. "Tau is a microtubule associated protein that functions to stabilize microtubules; however, abnormal aggregation of tau has been reported in a variety of neurodegenerative diseases including AD, frontotemporal dementia (FTD), progressive supranuclear palsy, LRRK2 PD, and others." (PMID 40128809, 2025).
amyotrophic lateral sclerosis (13 papers, 2013 to 2025). Amyotrophic lateral sclerosis (ALS) is a neurodegenerative disease characterized by progressive muscular paralysis reflecting degeneration of motor neurons in the primary motor cortex, corticospinal tracts, brainstem and spinal cord. "This means that this variant in HRNR occurs 1 in 300 Europeans, while other known pathogenic gene variants such as the Gly2019Ser variant of LRRK2 in PD (1 in 2,400 Europeans) or the Arg521Cys variant of FUS in amyotrophic lateral sclerosis (1 in 25,000 Europeans) are much less frequent." (PMID 35246273, 2022).